ZDHHC12 (zDHHC palmitoyltransferase 12)
Description:
Palmitoyltransferase that catalyzes the addition of palmitate onto various protein substrates. Has a palmitoyltransferase activity toward gephyrin/GPHN, regulating its clustering at synapses and its function in gamma-aminobutyric acid receptor clustering (By similarity). Thereby, indirectly regulates GABAergic synaptic transmission (By similarity). Negatively regulates NLRP3-driven inflammation. Catalyzes NLRP3 palmitoylation, leading to its degradation via the chaperone-mediated autophagy (CMA) process.
Synonyms: DHHC-12; ZNF400; FLJ14524; DHHC12
Tractability: Antibody: UniProt predicts a signal peptide or a membrane-spanning region; its Gene Ontology location is reachable by antibodies, with medium confidence.
Gene: Protein-coding gene on chromosome 9 (128,720,864 to 128,724,137, reverse strand). Ensembl gene ENSG00000160446.
Subcellular location: Golgi apparatus membrane; Endoplasmic reticulum membrane
Subcellular location (Human Protein Atlas): Nucleoplasm; Intermediate filaments
Gene Ontology:
Molecular function: palmitoyltransferase activity; protein binding; protein-cysteine S-palmitoyltransferase activity
Biological process: gephyrin clustering involved in postsynaptic density assembly; negative regulation of NLRP3 inflammasome complex assembly; peptidyl-L-cysteine S-palmitoylation; positive regulation of synaptic transmission, GABAergic; protein targeting to membrane
Cellular component: dendritic spine; endoplasmic reticulum; endoplasmic reticulum membrane; Golgi apparatus; Golgi membrane
Genetic constraint (gnomAD): Loss-of-function variants: 26 observed, 27.75 expected, observed/expected ratio (o/e) 0.94, 90% interval 0.69 to 1.3. The upper end of that interval is the gene's LOEUF score, 1.3, which puts it in group 5 of 6, group 1 being the genes least tolerant of losing a copy. Missense variants: 350 observed, 326.95 expected, observed/expected ratio (o/e) 1.07, 90% interval 0.98 to 1.17. Synonymous variants: 154 observed, 132.23 expected, observed/expected ratio (o/e) 1.16, 90% interval 1.02 to 1.33.
Homologues: Orthologues: chimpanzee ZDHHC12 (98% identical), dog ZDHHC12 (95% identical), pig ZDHHC12 (93% identical), rat Zdhhc12 (90% identical), guinea pig ZDHHC12 (89% identical), mouse Zdhhc12 (87% identical), macaque ZDHHC12 (64% identical), zebrafish zdhhc12b (53% identical), tropical clawed frog zdhhc12 (52% identical), zebrafish zdhhc12a (47% identical), Drosophila melanogaster Dnz1 (22% identical), Caenorhabditis elegans dhhc-7 (21% identical), and 3 more. Paralogues in human: ZDHHC7 (26% identical), ZDHHC14 (25% identical), ZDHHC1 (25% identical), ZDHHC3 (25% identical), ZDHHC20 (22% identical), ZDHHC18 (22% identical), ZDHHC19 (21% identical), ZDHHC9 (21% identical), ZDHHC23 (20% identical), ZDHHC6 (19% identical), ZDHHC11B (19% identical), ZDHHC15 (19% identical), and 5 more.
Diseases named in the same sentence as ZDHHC12 in open-access papers:
ZDHHC12 is named in the same sentence as 16 diseases in open-access papers, as found by Europe PMC text mining. Sharing a sentence is not in itself a finding about the gene and the disease. The quoted sentences say what the papers report.
ovarian carcinoma (7 papers, 2023 to 2025). A malignant neoplasm originating from the surface ovarian epithelium. "In ovarian cancer, zDHHC12 mediates S-palmitoylation of CLDN3 at C181, C182, and C184, which contributes to its proper localization and stabilization on the plasma membrane." (PMID 38415253, 2024). "ZDHHC12 mediates CLDN3 palmitoylation at three juxtamembrane cysteine residues, critical for ovarian cancer progression." (PMID 40977744, 2025). "Knocking down ZDHHC12 disrupts CLDN3 membrane targeting/stability and impairs ovarian cancer tumorigenicity, highlighting ZDHHC12 as a therapeutic target." (PMID 40977744, 2025). "zDHHC12 was shown to mediate the S‐acylation of membrane claudin‐3 (CLDN3), a tight junction protein that positively correlates with ovarian cancer progression." (PMID 39429488, 2024). "In an ovarian cancer cell line, CLDN3 or zDHHC12 silencing disrupted CLDN3 S‐acylation and abolished tumorigenesis." (PMID 39429488, 2024). "It has also been reported that ZDHHC12 promotes the stability of CLDN3 by affecting its cell membrane localization, which in turn promotes ovarian cancer progression." (PMID 38821916, 2024). "Knocking out zDHHC12 in ovarian cancer significantly inhibits the precise membrane localization and protein stability of CLDN3, as well as tumor occurrence in ovarian cancer cells." (PMID 39563863, 2024). "ZDHHC12 mediates palmitoylation of claudin 3 (CLDN3) at Cys103, Cys106, Cys181, Cys182, and Cys184 to enhance ovarian cancer progression and, reversely, defective CLDN3 palmitoylation inhibits membrane localization and protein stability of CLDN3, with a negative impact on ovarian cancer cell growth." (PMID 36018061, 2023). "zDHHC12 is upregulated in high‐grade serous ovarian cancer (HGSOC) and zDHHC12 knockdown or pharmacological inhibition with 2‐bromo‐palmitate sensitized HGSOC cells to cisplatin treatment in ovarian xenografts and in ascites‐derived organoid of platinum‐resistant ovarian cancer." (PMID 39429488, 2024).
glioma (6 papers, 2023 to 2025). A benign or malignant brain and spinal cord tumor that arises from glial cells (astrocytes, oligodendrocytes, ependymal cells). "zDHHC12 is also aberrantly expressed in gliomas, and knockdown of zDHHC12 reduces glioma cell survival, while overexpression of zDHHC12 not only promotes glioma cell growth but is also associated with immune cell infiltration." (PMID 38293675, 2023). "Specifically, we found that ZDHHC12 promotes glioma cell proliferation and the ZDHHCs-specific inhibitor, 2-bromopalmitate, significantly inhibits glioma cell proliferation." (PMID 37161425, 2023). "In gliomas, inactivation of ZDHHC15 blocked glioma cells proliferation by decreasing activation of Signal Transducer and Activator of Transcription 3 (STAT3) and knockdown of ZDHHC12 reduced the growth, migration, and invasion capabilities of glioma cells." (PMID 37759431, 2023). "While in vitro cell experiments demonstrate the role of zDHHC12 in the occurrence and progression of gliomas, further research is needed to collect more glioma samples and relevant clinical data to assess the performance of zDHHC12 in glioma diagnosis and prognosis." (PMID 39563863, 2024). "Further cell experiments indicated that zDHHC12 promotes the occurrence and progression of gliomas." (PMID 39563863, 2024). "Therefore, the role of zDHHC12 in gliomas may have therapeutic implications for glioblastoma immunotherapy." (PMID 38293675, 2023). "In our previous study, we found that ZDHHC4, ZDHHC9, ZDHHC12, ZDHHC15, and ZDHHC23 were abnormally expressed in glioma compared to normal brain tissues." (PMID 37161425, 2023).
autoimmune disease (2 papers, 2024). A disorder resulting from loss of function or tissue destruction of an organ or multiple organs, arising from humoral or cellular immune responses of the individual to their own tissue constituents. "The distinct functions of ZDHHC12-mediated palmitoylation in regulating the NLRP3 inflammasome and MAVS-mediated antiviral innate immunity may help balance immune responses and prevent autoimmune diseases." (PMID 39621307, 2024).
epilepsy (1 paper, 2014). A brain disorder characterized by episodes of abnormally increased neuronal discharge resulting in transient episodes of sensory or motor neurological dysfunction, or psychic dysfunction. "In fact, the ZDHHC12 gene is located in a region of chromosome 9 implicated in epilepsy and other neuropsychiatric disorders." (PMID 25025157, 2014).
glioblastoma (1 paper, 2024). The most malignant astrocytic tumor (WHO grade IV). "In glioblastoma, knockdown of ZDHHC12 restrains the growth, migration, and invasion capabilities." (PMID 38177255, 2024).
hepatocellular carcinoma (1 paper, 2025). A malignant tumor that arises from hepatocytes. "Similarly, CDX model intervention results indicated that the knockdown of HDAC8 significantly inhibited hepatocellular carcinoma growth in high‐palmitate diet‐fed mice, with or without the knockdown of ZDHHC12." (PMID 40787880, 2025). "ZDHHC12 knockdown in hepatocellular carcinoma cells decreased the level of HDAC8 expression, but when HSC70 or LAMP2A was knocked down, HDAC8 was not degraded, with or without ZDHHC12." (PMID 40787880, 2025).
melanoma (1 paper, 2024). A malignant, usually aggressive tumor composed of atypical, neoplastic melanocytes. "Thus, our collaborative research with W. Sheng’s team has shed light on the functional roles of ZDHHC12 in human and murine macrophages and ZDHHC4 in murine B16 melanoma cells, revealing their ability to promote MAVS-mediated immune responses." (PMID 39621307, 2024).
viral infection (1 paper, 2024). "Accordingly, Zdhhc12 deficiency apparently impaired RNA virus–induced type I IFN responses, and Zdhhc12-deficient mice were highly susceptible to lethal viral infection." (PMID 39621307, 2024). "We next investigated whether ZDHHC12 regulates the type I IFN signaling pathway via its enzymatic activity and found that mutation of the ZDHHC12 enzymatic site abrogated its ability to upregulate type I IFN signaling during viral infection." (PMID 39621307, 2024). "A fluorescence resonance energy transfer (FRET) assay further confirmed that there was a strong interaction between MAVS and ZDHHC12 upon viral infection." (PMID 39621307, 2024). "The abolishment of Zdhhc12 led to the downregulation of a variety of ISGs upon viral infection." (PMID 39621307, 2024). "Here, we demonstrated that the palmitoylation of MAVS at cysteine 79 (C79), which is catalyzed mainly by the palmitoyl S-acyltransferase ZDHHC12, was essential for MAVS aggregation and antiviral innate immunity upon viral infection in macrophages." (PMID 39621307, 2024).
tumor (4 papers, 2024 to 2025). "A subcutaneous tumorigenesis assay demonstrated that ZDHHC12 knockdown attenuated the tumor‐promoting effects of a high‐palmitate diet." (PMID 40787880, 2025). "This suggests that ZDHHC12/24 and APT2 may inhibit tumor-associated CD8+ T cells, thereby aggravating the pathogenesis of LUAD and promoting tumor growth." (PMID 38177255, 2024). "Therefore, we hypothesize that ZDHHC12 might modify BAX palmitoylation to control tumor cell death, thereby affecting tumor cell proliferation." (PMID 38177255, 2024). "The upregulation of 24 palmitoylation regulating genes in tumor tissues (e.g., ZDHHC12, LYPLA1) compared to normal tissues suggests a tumor-promoting role for palmitoylation in LGG." (PMID 40535771, 2025). "Our integrated analysis of HCC single‐cell RNA sequencing datasets revealed that ZDHHC12 is expressed predominantly in HCC cells, with particularly high expression observed in the most highly malignant tumor cells." (PMID 40787880, 2025).
cancer (3 papers, 2022 to 2025). A tumor composed of atypical neoplastic, often pleomorphic cells that invade other tissues. "Analysis of The Cancer Genome Atlas (TCGA) revealed a positive correlation between SMARCA4 and ZDHHC12 expression levels across multiple cancer types, including HCC." (PMID 40787880, 2025). "Currently, the role of ZDHHC12 in cancer remains poorly understood." (PMID 40787880, 2025). "In lean NASH-HCC, methylation differences were seen in genes involved with cancer progression and prognosis (including HCC), such as CHCHD2, FSCN1, and ZDHHC12, and lipid metabolism, including PNPLA6 and LDLRAP1." (PMID 36474183, 2022).
ZDHHC12 also shares sentences with these, for which no sentence is quoted: Alzheimer disease (1 paper); Anxiety (1); lymph node metastasis (1); mild cognitive impairment (1); neuroblastoma (1); serous ovarian cancer (1).